XAF1 (XIAP associated factor 1)
Diseases named in the same sentence as XAF1 in open-access papers (continued):
Sharing a sentence is not in itself a finding about the gene and the disease.
cancer (continued). "In this report, we investigated the role of basal xaf1 promoter methylation in xaf1 expression and assessed the responsiveness of cancer cell lines to XAF1 induction by IFN-β." (PMID 17376236, 2007). "Together, these results demonstrate that the induction of endogenous XAF1 by IFN-β plays a critical role in sensitizing cancer cells to TRAIL-induced cell death." (PMID 17376236, 2007). "Our results indicate that mechanisms, in addition to DNA methylation, are responsible for the control of XAF1 expression in cancer cells." (PMID 17376236, 2007). "In cancer cells, we find a strong correlation between methylation status of the xaf1 promoter and baseline gene expression at the transcript level." (PMID 17376236, 2007). "In contrast, the SF539 cell line expresses substantial amounts of XAF1 protein, compared to other cancer cell lines examined." (PMID 17376236, 2007). "In this regard, it would be interesting to examine the correlation between DNA methyltransferases expression and xaf1 promoter methylation status in various cancer cell lines to evaluate their response to IFN-β-induced apoptosis." (PMID 17376236, 2007). "First, we validated the relationship between xaf1 silencing and promoter hypermethylation across four cancer cell lines HeLa, SK-N-AS, SF539 and SF295, that was to date, unexplored in this context." (PMID 17376236, 2007). "XAF1 has been independently identified in several screens as a key mediator of apoptosis and is shown to dramatically sensitize cancer cells to apoptotic triggers such as TNF-related apoptosis-inducing ligand (TRAIL) and etoposide treatments." (PMID 17376236, 2007). "A potential pitfall of the use of IFN to induce xaf1 expression is the frequent hypermethylation of the xaf1 promoter observed in many cancer cell lines." (PMID 17376236, 2007). "Xaf1 promoter methylation represents an initial mechanism of apoptosis resistance displayed by cancer cells." (PMID 17376236, 2007). "In accordance with previous reports, we find a strong inverse correlation between xaf1 promoter methylation and baseline transcript in four cancer cell lines tested." (PMID 17376236, 2007). "Furthermore, it was discovered that the expression levels of XAF1 are influenced by the hypermethylation of its promoter region, indicating a regulatory mechanism in the development of cancer." (PMID 40718833, 2025). "TRIM28 regulation of XAF1 was verified in multiple cancer cell lines." (PMID 39532800, 2024). "XAF1 has been shown to inhibit proliferation and induce apoptosis and ER stress in cancer cells." (PMID 39266576, 2024). "We hypothesized that this anti-miR-1976 strategy only applied to XAF1-positive cancer cells, since miR-1976 regulated XAF1 protein expression." (PMID 37189754, 2023). "The role of XAF1 is discussed in different kinds of cancers." (PMID 36132546, 2022). "To explore the role for XAF1 in ER stress response, we initially examined whether it affects apoptotic response to ER stress using 24 human cancer cell lines." (PMID 35902580, 2022). "The expression of XAF1, a pro‐apoptotic protein, is frequently suppressed in human cancers." (PMID 35810383, 2022). "XAF1 expression is reduced in various cancers, including ovarian." (PMID 35810383, 2022). "Interestingly, the levels of GABARAP were significantly higher when compared to Xaf1 in normal and malignant breast tissues as well as cancer cell lines from various organs." (PMID 27124579, 2016). "In cancer, the XAF1 gene is commonly silenced by CpG-dinucleotide hypermethylation of its promoter." (PMID 26443201, 2015). "Studies suggested that a high level of XIAP to XAF1 expression in cancer cells may provide a survival advantage through the relative increase of XIAP anti-apoptotic function." (PMID 24874286, 2014).
cancer (continued). "XAF1 was silent or expressed lowly in most human malignant tumors." (PMID 24980821, 2014). "Likewise, reduced XAF1 expression has been described in several human cancers, and XAF1 has been suggested to represent a tumorsuppressor." (PMID 24281211, 2010). "Finally, our results strengthen the importance of XAF1 expression in IFN-β-mediated sensitization to TRAIL-induced cell death in cancer cells." (PMID 17376236, 2007). "Furthermore, our study provides evidence that XAF1 is a crucial interferon-stimulated gene (ISG) mediator of IFN-induced sensitization to TRAIL in cancer." (PMID 17376236, 2007). "Interestingly, under specific stress pressure, the heat-shock transcription factor 1 (HSF1) was demonstrated to function as a negative regulator of xaf1 expression in various gastroinstestinal cancer tissues and cell lines." (PMID 17376236, 2007). "Several ISGs, such as OAS family members and the tumor suppressors XAF1 and IRF7, have been shown to play crucial roles in counteracting cancer progression, and their increased expression is associated with the inhibition of cell growth and the promotion of the apoptosis of cancer cell lines." (PMID 28184177, 2017). "XAF1 is poorly expressed in many cancers despite the lack of association with any inactivating mutation or deletion, suggesting that epigenetic silencing or upstream regulation of XAF1 could be the key to controlling its expression." (PMID 27097110, 2016). "The transfection of BNC2 to A549 cells led to the up-regulation of numerous ISGs, of which a subset (XAF1, IRF7, OAS family) is known to inhibit cancer growth and promote the apoptosis of cancer cells." (PMID 28184177, 2017). "Concordantly, the reduced expression of XAF1 and OAS family members has been observed in several cancer cell lines." (PMID 28184177, 2017). "Other negatively regulating proteins are XAF-1, which binds XIAP and was found to be downregulated in a majority of the NCI60 cancer cell line panel, and TRAF3, which promotes the degradation of the cIAP1/2-TRAF2-complex." (PMID 27167336, 2016). "In cancer, methylation negatively affects the interaction between CTCF and the XAF1 promoter, disabling the protective epigenetic actions of CTCF against the closed-chromatin configuration." (PMID 26443201, 2015). "XAF1 has been identified as an interferon (IFN)-inducible tumour suppressor gene, which's expression sensitizes cancer cells to several apoptotic stimuli." (PMID 19664236, 2009). "Finally, XAF1 itself may potentially provide a therapeutic agent, as its induction by adenoviral delivery recently proved to be promising strategy for the treatment of cancer." (PMID 19664236, 2009). "We found a strong variability in xaf1 promoter methylation profile and responsiveness to IFN-β across the four cancer cell lines studied." (PMID 17376236, 2007). "Four cancer cell lines, SF295, SF539, SK-N-AS and HeLa were selected to investigate the effect of xaf1 promoter methylation on IFN-β mediated xaf1 induction." (PMID 17376236, 2007). "investigations into the role of environmental factors in the origin of the p.R337H and XAF1 p.E134* variants (even though no de novo variant has been identified to date) and/or in the formation of ACC and other forms of cancer." (PMID 40558276, 2025). "XAF1, TRIM31, G0S2 and IFI6 have known roles in apoptosis or its prevention, while PAX7, TRIM31 and PNMA8A are involved in cell development/development of cancer." (PMID 38990812, 2024). "Despite their structural similarity and frequent dysregulation in multiple human cancers, only TRIM28 shows the property to interact with XAF1, suggesting that XAF1 may recognize unique amino acid sequences in the RING domain of TRIM28." (PMID 39532800, 2024).
cancer (continued). "In addition, a strong inverse correlation was identified between XAF1 and GRP78 levels in 21 human cancer cell lines." (PMID 35902580, 2022). "This was not the case for several other cancer types, highlighting XAF1 role in a tissue‐specific manner." (PMID 33734579, 2021). "Interestingly, these drugs increased ROS generation in cancer cells; co-treatment with N-acetyl-cysteine (NAC), a generally used antioxidant, reduced ROS generation and XAF-1 expression." (PMID 33130818, 2020). "Similarly, in this study, we also found that mRNA and protein expression levels of XAF1 were very low or undetectable in three HCC cell lines and HCC tissues compared to those in the adjacent non-cancer tissues." (PMID 24980821, 2014). "IHC showed that XAF1 was expressed in non-HCC tissues but not in cancer tissues." (PMID 24980821, 2014). "Besides DAPK1, 5-Aza and DNMT1 antisense oligonucleotides are able to restore the sensitivity of cancer cells to IFN-triggered apoptosis despite the re-expression of the pro-apoptotic gene RASSF1A and XAF1 which are frequently silenced by epigenetic mechanisms." (PMID 21108789, 2010). "The result showed that the mRNA and protein expressions of XAF1 were lower in three HCC cell lines SMMC-7721, BEL-7404 and Hep G2 cancer cells compared non-cancer tissue of liver." (PMID 24980821, 2014). "Importantly, in cancer cell lines, the lack of CTCF regulation on the XAF1 promoter via methylation on its cognate binding site partially blocks its transcriptional responsiveness to two well-known transcriptional activators, TNF-α or IFN-α." (PMID 26443201, 2015).
infection (19 papers, 2010 to 2024). The state of being infected such as from the introduction of a foreign agent such as serum, vaccine, antigenic substance or organism. "During PR8 and WSN infection, much less induction of XAF1 was observed in the Ifnar1−/− PMs than in the wide-type (WT) cells." (PMID 35972291, 2022). "Infection with RNA viruses upregulates XAF1 expression by inducing its master TF IRF1, and the elevated XAF1 stabilizes the IRF1 protein to induce more antiviral IRF1 target genes." (PMID 35972291, 2022). "After this expression of XAF1 was enhanced, as much as 28% of cells entered irreversible apoptosis 72 h after infection." (PMID 34920753, 2021). "Further research found that DENV2 induces ECs apoptosis through XIAP-associated factor 1 (XAF1)-dependent pathway, XAF1 is one of the interferon-inducing genes, it upregulates caspase-3 36 h after infection and mediates cell apoptosis." (PMID 33841381, 2021). "Following this enhanced expression of XAF1, as much as 28% of the cells had entered irreversible apoptosis by 72 hrs post-infection, at which point the balance of survival had been disrupted." (PMID 26244642, 2015). "To determine the mechanisms of XAF1-induced apoptosis, we detected the expressions of apoptosis-related proteins 48 hours post-infection of Ad5/F35-XAF1 in SMMC-7721 cells by Western blot." (PMID 24980821, 2014). "Therefore, XAF1 modifies chromatin structure to enhance antiviral immunity by targeting TRIM28 during infection." (PMID 39532800, 2024). "Apoptosis related proteins (ANXA5 and Caspase-13/CASP4) and CAPN14, USP18, XAF1, Caspase-13/CASP4, and ISG12 transcripts were significantly upregulated after infection with swH1N1 compared to controls." (PMID 39247193, 2024). "Infection with IAV H1N1 strains WSN and PR8 dramatically induced XAF1 transcription in human PBMCs and A549 cells." (PMID 35972291, 2022). "Infection with another two RNA viruses, vesicular stomatitis virus (VSV) and SeV, also highly induced XAF1 expression in these human cells." (PMID 35972291, 2022). "A series of IFN-stimulated and IFN-inducible genes are highly expressed post-infection, and include ISG15, IFI6, IFI44, IFI44L, IRF27, IFIT1, IFIT3, and XAF1." (PMID 26244642, 2015). "The 17 DEGs upregulated after infection with huH1N1 were shared with the swH1N1 infection (DDX58 (RIG-I), RSAD2 (Viperin), MX2, MX1, OAS1, ANGPTL4, IRF7, ISG15, IFIT1, ISG12(A), DDX60, BST2, IFI44, XAF1, LGALS3BP, RTP4, and IFI6)." (PMID 39247193, 2024). "Overexpression of XAF1 upregulated IRF1 protein levels in a dose-dependent manner in the HEK293T cells without any infection or stimulation, which further suggested that XAF1 regulates the turnover of the IRF1 protein." (PMID 35972291, 2022). "Pro-apoptotic molecules XAF1, BID, cyto c, CASP10, AIFM2, were significantly up-regulated after infection with N-PRRSV, which may induce apoptosis of virus-infected cells." (PMID 20614006, 2010). "SARS-CoV-2-Δ8 infection showed a trend of increasing IFN signaling (IFNλ3, interferon-stimulated gene [ISG15], and MX1, P values 0.4337, 0.1126, and 0.2285, respectively) as compared to WT at 3 dpi, while reducing IFN-stimulated gene levels (IFNλ3, ISG15, IFIT1, OAS1, and XAF1) at 6 dpi." (PMID 37623322, 2023).
XAF1 also shares sentences with these, for which no sentence is quoted: clear-cell renal cell cancer (3 papers); non-small cell lung carcinoma (3); primary Sjögren syndrome (2); urothelial carcinoma (2); autism (1); autoimmune disease (1); Autoimmunity (1); brain tumors (1); Cerebral ischemia (1); cervical carcinoma (1); colorectal tumors (1); endothelial dysfunction (1); Gastric Tumors (1); Granuloma (1); heart failure (1); Hepatitis (1); ischemia (1); lung squamous cell carcinoma (1); lymphopenia (1); measles (1); metastatic melanoma (1); nephritis (1); Obesity (1); pancreatic adenocarcinoma (1); periodontitis (1); prostate tumors (1); pterygium (1); respiratory infection (1); rheumatoid arthritis (1); SARS-CoV infections (1).
A further 6 diseases each share a sentence with XAF1 in 1 paper.